CDK8 (cyclin dependent kinase 8)
Description:
Component of the Mediator complex, a coactivator involved in regulated gene transcription of nearly all RNA polymerase II-dependent genes. Mediator functions as a bridge to convey information from gene-specific regulatory proteins to the basal RNA polymerase II transcription machinery. Mediator is recruited to promoters by direct interactions with regulatory proteins and serves as a scaffold for the assembly of a functional pre-initiation complex with RNA polymerase II and the general transcription factors. Phosphorylates the CTD (C-terminal domain) of the large subunit of RNA polymerase II (RNAp II), which may inhibit the formation of a transcription initiation complex. Phosphorylates CCNH leading to down-regulation of the TFIIH complex and transcriptional repression. Recruited through interaction with MAML1 to hyperphosphorylate the intracellular domain of NOTCH, leading to its degradation. Selectively regulates the interferon response by phosphorylating the transcription factor STAT1 transactivation domain (By similarity).
Synonyms: K35; IDDHBA
Tractability: Small molecule: a drug acting on it is in phase 2 or 3 trials; a structure with a bound ligand is known; a high-quality ligand is known; it belongs to a druggable protein family. PROTAC: it is named in the literature on targeted protein degradation; ubiquitination databases record sites on it; a small molecule that binds it is known.
Target class: Protein Kinase; CMGC protein kinase CDK family; CMGC protein kinase group; CMGC protein kinase CDK8 subfamily; Kinase; Enzyme
Chemical probes: BI-1347 (high quality), CCT251545 (high quality), Cortistatin-A, JH-XI-10-02, JH-XI-10-02 (high quality), MSC2530818 (high quality)
Gene: Protein-coding gene on chromosome 13 (26,253,891 to 26,420,982, forward strand). Ensembl gene ENSG00000132964.
Subcellular location: Nucleus
Subcellular location (Human Protein Atlas): Nucleoplasm
Pathways (Reactome):
Disease: Constitutive Signaling by NOTCH1 HD+PEST Domain Mutants; Constitutive Signaling by NOTCH1 PEST Domain Mutants; RSV-host interactions
Gene expression (Transcription): Generic Transcription Pathway; MLL4 and MLL3 complexes regulate expression of PPARG target genes in adipogenesis and hepatic steatosis
Signal Transduction: NOTCH1 Intracellular Domain Regulates Transcription; SMAD2/SMAD3:SMAD4 heterotrimer regulates transcription
Developmental Biology: Transcriptional regulation of white adipocyte differentiation
Metabolism: PPARA activates gene expression
Gene Ontology:
Molecular function: protein binding; protein kinase activity; cyclin-dependent protein serine/threonine kinase activity; ATP binding; protein serine kinase activity; RNA polymerase II CTD heptapeptide repeat kinase activity
Biological process: positive regulation of transcription by RNA polymerase II; regulation of cell cycle
Cellular component: CKM complex; cyclin-dependent protein kinase holoenzyme complex; mediator complex; nucleolus; nucleus; protein-containing complex; nucleoplasm
Genetic constraint (gnomAD): Loss-of-function variants: 11 observed, 28.18 expected, observed/expected ratio (o/e) 0.39, 90% interval 0.25 to 0.65. The upper end of that interval is the gene's LOEUF score, 0.65, which puts it in group 2 of 6, group 1 being the genes least tolerant of losing a copy. Missense variants: 137 observed, 267.68 expected, observed/expected ratio (o/e) 0.51, 90% interval 0.44 to 0.59. Synonymous variants: 76 observed, 96.68 expected, observed/expected ratio (o/e) 0.79, 90% interval 0.65 to 0.95.
Homologues: Orthologues: chimpanzee CDK8 (100% identical), rabbit CDK8 (100% identical), dog CDK8 (99% identical), pig CDK8 (99% identical), macaque CDK8 (99% identical), mouse Cdk8 (99% identical), tropical clawed frog cdk8 (97% identical), zebrafish cdk8 (97% identical), guinea pig CDK8 (93% identical), rat Cdk8 (90% identical). Paralogues in human: CDK19 (84% identical), CDK13 (31% identical), CDK12 (30% identical), CDK16 (29% identical), CDK1 (28% identical), CDK11A (28% identical), CDK11B (28% identical), CDK17 (28% identical), CDK7 (28% identical), CDKL5 (27% identical), CDK3 (26% identical), CDKL2 (26% identical), and 14 more.
Diseases named in the same sentence as CDK8 in open-access papers:
CDK8 is named in the same sentence as 137 diseases in open-access papers, as found by Europe PMC text mining. Sharing a sentence is not in itself a finding about the gene and the disease. The quoted sentences say what the papers report.
breast carcinoma (44 papers, 2015 to 2026). "Reduced relapse-free survival in patients with breast cancer is associated with elevated levels of CDK8 and its interacting proteins." (PMID 40361480, 2025). "In HER2-positive breast cancer, high expression of CDK8 is associated with an increased risk of recurrence after treatment, suggesting a role of CDK8 in the development of resistance to targeted therapy." (PMID 40940746, 2025). "Dysregulation of cyclin-dependent kinase 8 (CDK8) activity has been associated with many diseases, including colorectal and breast cancer." (PMID 38791449, 2024). "MacroH2A variants in contrast limit cell proliferation by silencing CDK8 in melanoma and breast cancer." (PMID 33167489, 2020). "In the context of breast cancer, CDK8 along with S-phase kinase-associated protein 2 (Skp2) has been shown in tissue samples to positively correlate with stage of breast cancer." (PMID 33291686, 2020). "We have previously carried out such analysis for breast cancer, showing that CDK8 and related genes were associated with the failure of systemic therapy in all the principal molecular subtypes of breast cancer." (PMID 31382571, 2019). "The overexpression of CDK8 and Skp2, accompanied by low levels of mH2A1, is associated with an adverse prognosis in breast cancer patients." (PMID 31248103, 2019). "CDK8 expression was found to be upregulated in breast cancers and linked to tumour progression." (PMID 36235128, 2022). "Survival analysis of breast cancer patients revealed that increased CDK8 expression was associated with inferior overall survival (OS), higher expression of CDK7 or CDK8 was associated with inferior relapse-free survival (RFS), but higher expression of CDK13 was associated with favorable RFS and OS." (PMID 33686962, 2021). "Inhibition of ER-mediated transcriptional signaling by CDK8/19 inhibitors was associated with a strong inhibition of the mitogenic effect of estrogen in ER-positive breast cancer cell lines and with cytostatic growth inhibition of ER-positive cells in estrogen-containing media." (PMID 28147342, 2017). "Currently, both CDK8 and Mcl-1 are being actively pursued as therapeutic targets in breast cancer in general and triple-negative breast cancer specifically." (PMID 41596544, 2026). "CDK8 inhibition has been explored in estrogen receptor (ER)-positive breast cancer, acute myeloid leukemia, prostate cancer, and glioblastoma." (PMID 41493967, 2026). "The authors concluded that capsaicin inhibited breast cancer cell viability and migration by suppressing CDK8 expression and the PI3K/Akt/Wnt/β-catenin pathway." (PMID 40001961, 2025). "It has been proven that CAP alters the expression of the cyclin-dependent kinase 8 (CDK8) protein within the breast carcinoma cells, resulting in the cells entering a G2/M arrest during the cell cycle." (PMID 40362978, 2025). "It has been reported that when CDK8 expression is high in various carcinomas, especially breast cancer, a poor prognosis is found." (PMID 39604563, 2025). "CDK8 in complex with cyclin C is a transcriptional regulator that mediates several carcinogenic pathways in breast cancer." (PMID 37175852, 2023). "In breast cancer, knockdown of CDK8 impairs EMT and increases tumor cell clearance via the CDK8/PDL1 axis." (PMID 36132137, 2022). "In particular, CDK8 inhibitors have been used in acute myelogenous leukaemia and several other types of cancers, including breast cancer." (PMID 36292630, 2022). "We have analyzed the effects of CDK8/19 inhibitors on the development of adaptive resistance in cell lines derived from breast cancer (gefitinib, erlotinib) and colon cancer (cetuximab)." (PMID 33445730, 2021). "In our study, increased mRNA levels of CDK8 were significantly associated with inferior OS and RFS for patients with breast cancer in the TCGA portal and in the UALCAN and Kaplan-Meier Plotter databases." (PMID 33686962, 2021).
breast carcinoma (continued). "We have used a murine model of orthotopic breast cancer to study the tumor-intrinsic role of CDK8 in TNBC." (PMID 34689158, 2021). "CDK8 has been implicated in the regulation of EMT in pancreatic, ovarian, and HER2-enriched breast cancer cell lines and promotes metastasis of colon cancer." (PMID 34689158, 2021). "We used breast cancer cell lines to analyze the effects of CDK8/19 inhibitor senexin B on the development of resistance to small-molecule EGFR inhibitors gefitinib and erlotinib." (PMID 33445730, 2021). "A recent study describes CDK8 as a potential therapeutic target in estrogen receptor (ER)-positive breast cancer cells, showing that estrogen-induced transcription depends on CDK8 kinase activity." (PMID 34689158, 2021). "At the mRNA level, overexpression of CDK7 or CDK8 was associated with inferior prognosis, whereas higher CDK13 expression was associated with favorable prognosis in breast cancer patients." (PMID 33686962, 2021). "Along with available preclinical data, these findings therefore support a pro-oncogenic role for CDK8 in breast cancer." (PMID 33686962, 2021). "Our experiments further demonstrate that NK cells, in principle, possess the ability to control primary tumor growth in breast cancer, but that NK-cell-mediated tumor surveillance is blocked by the presence of CDK8 in E0771 tumor cells." (PMID 34689158, 2021). "Recent in silico studies have revealed an inverse correlation between recurrence-free survival and the level of cyclin-dependent kinase 8 (CDK8) in breast cancer patients." (PMID 34689158, 2021). "The CDK8–PD-L1 axis is found in mouse and human TNBC cells, underlining the importance of CDK8-driven immune cell evasion in these highly aggressive breast cancer cells." (PMID 34689158, 2021). "Knockout of CDK8/19 via CRISPR-Cas9 inhibits ER positive breast cancer cell estrogen-induced transcription." (PMID 32765953, 2020). "For example, macroH2A limits the proliferative potential of melanoma and breast cancer cells by hindering the expression of cyclin-dependent kinase 8 (CDK8)." (PMID 33167489, 2020). "In chem-naïve breast cancer patients (sub-class unspecified), tumor specimens demonstrated lower CDK8-targeting micro-RNA than in adjacent tissue." (PMID 33291686, 2020). "It is interesting to note that CDK8 is amplified in a significant number of breast cancers, but low β–catenin levels are correlated with poor prognosis." (PMID 33291686, 2020). "Since this initial observation, CDK8 has been implicated as a potential driver of other cancers including acute myelogenous leukemia (AML) and some breast cancers." (PMID 33291686, 2020). "Small-molecule CDK8/19 inhibitors have recently entered or are entering clinical trials, starting with breast cancer and acute myeloid leukemia (AML)." (PMID 31382571, 2019). "CDK8/CDK19 inhibitors suppress the growth of estrogen receptor-positive breast cancer cells and reduce the emergence of estrogen-independent cells." (PMID 31248103, 2019). "An example of such a marker is the GREB1 gene in estrogen receptor (ER)-positive breast cancers, which is coregulated by ER and CDK8/19 in this tumor type." (PMID 31717492, 2019). "The other cancers with a substantial frequency of CDK8/CDK19/CCNC gene amplification were breast cancers and sarcomas." (PMID 31382571, 2019). "Cdk8 overexpression in breast cancer tumors also exhibits a strong positive correlation with Myc expression." (PMID 30621145, 2019). "Later on Cdk8 was reported to play a role in many other cancers such as pancreatic cancer, breast cancer, and melanoma." (PMID 31552016, 2019). "In the same study, we found that higher expression of CDK8, CDK19 and Cyclin C is associated with shorter relapse-free survival in human breast cancers." (PMID 28147342, 2017).
breast carcinoma (continued). "In the present study, we have discovered that CDK8 inhibition also inhibits ER signaling and suppresses the growth of ER-positive breast cancer cells, the most common type of breast cancer, in vitro and in vivo." (PMID 28147342, 2017). "Treatment of estrogen-deprived ER-positive breast cancer cells with CDK8/19 inhibitors strongly impeded the development of estrogen independence." (PMID 28147342, 2017). "We have extended our previous analysis of CDK8 expression in breast cancer and investigated correlations between CDK8 and ER expression using a microarray database of 3,491 breast cancer patients." (PMID 28147342, 2017). "Our analysis was able to confirm several recently published studies such as the overexpression of MED1 in breast cancer at the protein level or the overexpression of subunits of the kinase module (especially CDK8) in colon cancer on the mRNA level." (PMID 27050271, 2016). "A role for CDK8 in breast cancer has been suggested through siRNA silencing in breast cancer cell lines which leads to a significant decrease in proliferation." (PMID 25625291, 2015). "Research has shown that CDK8 expression and estrogen receptor (ER) levels in breast cancer are negatively correlated, suggesting that CDK8 may influence ER signaling pathways." (PMID 40361480, 2025). "Furthermore, overexpression of CDK8 drives tumor cell proliferation and promotes breast cancer progression." (PMID 40940746, 2025). "The mechanism may rely on capsaicin reducing the protein expression levels of CDK8, Wnt and β-catenin, and further inhibiting CDK8/Wnt/β-catenin signaling to suppress breast cancer cell migration." (PMID 38734935, 2024). "Moreover, the involvement of CDK8 in the pathogenesis of gastric cancer, breast cancer, prostate cancer, melanoma, and acute myeloid leukemia highlights its potential as a promising therapeutic target for various malignancies." (PMID 38606172, 2024). "Research has shown that CDK8 enhances the estrogen receptor (ER) in breast cancer by stimulating Ser2 phosphorylation of estrogen-induced RNA pol II CTD, thus more effectively assisting in the transcription process of ER-inducible genes, such as GREB1、CXCL12 and TFF1." (PMID 38606172, 2024). "In particular, CDK8-mediated activation of the Wnt-β–catenin signaling pathway and the transcription of estrogen-inducible genes contribute, respectively, to oncogenesis in colorectal and mammary tumors, making CDK8 an oncogene of interest." (PMID 38791449, 2024). "From these plants, a total of 200 phytocompounds (30 for Zingiber officinale Roscoe; 41 for Cuminum cyminum L.; 41 for Piper nigrum L.; 42 for Curcuma longa L., and 46 for Allium sativum L.)were screened against various breast cancer protein targets (i.e., CDK8, PR and EFGR)." (PMID 36235128, 2022). "In silico investigations of patient samples revealed an inverse correlation between recurrence-free survival and cyclin-dependent kinase 8 (CDK8) levels in various breast cancer types, however, a correlation separately for TNBC patients has not yet been reported." (PMID 34689158, 2021). "Targeting CDK8 may be beneficial through different aspects; first, by dampening the invasive and pro-metastatic behavior of the breast cancer cells, and, second, by preventing evasion from NK cells." (PMID 34689158, 2021). "Furthermore, miRNA-mediated knockdown of CDK8 reduces the proliferation and migration of breast cancer cells." (PMID 33291686, 2020). "This suggests that the roles of CDK8 and β–catenin differ between colon cancers and breast cancers." (PMID 33291686, 2020). "The identification of CDK8 as a colon cancer oncogene and regulator of β–catenin protein has spurred intense interest in the potential involvement of CDK8 in other types of cancer including breast cancer." (PMID 33291686, 2020). "In breast cancer, the miRNA targets CDK8 in the cell cycle pathway." (PMID 32169117, 2020).
breast carcinoma (continued). "Importantly, this study also presented positive correlations between Cdk8 and both cyclin C and Med13 in breast cancers." (PMID 30621145, 2019). "Indications of the mechanisms come from human pancreatic and ovarian cell lines and a murine breast cancer model, in which the inhibition of CDK8/CDK19 counteracts EMT by upregulating E-cadherin, downregulating Snail1 and Snail2, and reducing tumor cell invasion." (PMID 31248103, 2019). "Analysis of the transcriptome data of 968 breast cancer patients has uncovered increased levels of CDK8/CDK19 paralleled by enhanced levels of cyclin C and MED13 compared to samples from patients with benign or hyperplastic breast cancers and from normal mammary tissues." (PMID 31248103, 2019). "CDK8 has been reported as an oncoprotein in colorectal and gastric cancers and further evidence points to its role in promoting cell proliferation in melanoma and breast cancer." (PMID 25625291, 2015). "Furthermore, CDK8/19i potentiated growth inhibitory effects of the estrogen antagonist fulvestrant in breast cancer cells, reversed castration resistance of advanced prostate cancers, stimulated tumor surveillance by NK cells and enhanced the antitumor effects of CAR-T cells." (PMID 39955308, 2025). "Evidence has demonstrated that CDK8 plays an oncogenic role in cancers, by stimulating epithelial-to-mesenchymal transition in pancreatic cancer, facilitating migration and invasion in prostate cancer, and promoting proliferation and metastasis in breast cancer, melanoma and colorectal cancers." (PMID 30524203, 2018). "However, CDK8 therapy could potentially have another positive anticancer effect: CDK8 has been previously shown to be an oncogenic driver in colorectal cancer, breast cancer, and melanoma." (PMID 27148271, 2016). "Migration and cell viability was also tested with the MTT array discovering that cyclin-dependent kinase 8 (CDK8) was inhibited by capsaicin, reducing the viability of human breast cancer cells." (PMID 40001961, 2025). "Senexin B and SNX631 (Selective CDK8/19 inhibitors) have shown synergistic interactions with lapatinib and trastuzumab in a group of HER2+ breast cancer cell lines, overcoming and preventing cell resistance to HER2-targeted drugs." (PMID 38606172, 2024). "Chemical inhibition of CDK8/CDK19 or genetic knockdown of CDK8 impaired cell growth and progression of this breast cancer type in vitro and in vivo." (PMID 34689158, 2021). "In accordance with previous studies, focusing on breast cancer patients with molecular subtypes luminal A and B, basal, and HER2+, we extended the link of CDK8 expression to overall survival to a selected TNBC patient cohort." (PMID 34689158, 2021). "Whereas CDK8 is not required for cell proliferation or cell survival of TNBC, CDK8 promotes regrowth of primary tumors and subsequently the metastatic spread of TNBC cells in a murine orthotopic breast cancer model." (PMID 34689158, 2021). "The results revealed that the mRNA expression of CDK7, CDK8, CDK9, CDK10, CDK12, CDK19, and CDK20 was upregulated in patients with breast cancer." (PMID 33686962, 2021). "The SKP2-macroH2A1-CDK8 axis controls p27 protein expression in breast cancer cells: CRL1SKP2 targets macroH2A1 degradation, which in turn leads to increased CDK8 expression and CDK8-induced p27 proteolysis." (PMID 33005013, 2020). "The correlation of expression of leptin receptor (OBR), leptin-targeted genes (CDK8, NANOG, and RBP-Jk), and breast cancer (BC) patient survival was determined from The Cancer Genome Atlas (TCGA) mRNA data." (PMID 32471192, 2020). "In contrast, CDK8, CDK19, and CCNC showed similar amplification frequencies in breast cancers and sarcomas." (PMID 31382571, 2019). "In particular, co-amplification of CDK8 with CCNC and/or CDK19 was found in some cases of prostate and breast cancer." (PMID 31382571, 2019).